IL6 (interleukin 6)
Diseases named in the same sentence as IL6 in open-access papers (continued):
Sharing a sentence is not in itself a finding about the gene and the disease.
Arthritis (867 papers, 2005 to 2026). Inflammation of a joint. "Medium-dose triptolide not only significantly reduced arthritis scores and levels of IL-6 and IL-17A, but also caused substantially less ovarian damage (E2, estrous cycles) compared to the high-dose group." (PMID 40918529, 2025). "We also measured the serum levels of two crucial inflammation‐related cytokines, TNF‐α and IL‐6, which are intricately linked to arthritis pathogenesis." (PMID 40626319, 2025). "In arthritis-susceptible Lewis rats that were injected with IL-27, there was reduced expression of IL-17, RORγt, IL-23, and IL-6 in arthritic joints, and the joint space was clear with minimal MNC infiltration of the synovial tissue." (PMID 38566992, 2024). "Increased arthritis disease activity was associated with higher levels of inflammatory cytokines (IL-6, TNF and CRP) and immunoregulatory cytokine IL-10 (p<0.05)." (PMID 38507338, 2024). "Tumor necrosis factor-alpha (TNF-α) and interleukin-6 (IL-6) are cytokines that play pivotal roles in inflammatory processes, including those associated with arthritis." (PMID 38817355, 2024). "Studies have shown that they can enhance susceptibility to colorectal cancer and arthritis by interfering with IL-6/STAT3 signaling pathway and bile acid metabolism." (PMID 37908541, 2023). "SKG arthritis symmetrically affects joints and is associated with the elevation of key RA cytokines including IL‐6, IL‐1β, and TNF." (PMID 36890657, 2023). "It was also found that in mice transgenic for IL-1α (activation of IL-1 signalling) and prone to arthritis, IL-6 deficiency resulting from knockout of the corresponding gene reduces, but does not cancel, pathological changes in the joints." (PMID 36911042, 2023). "Decreased arthritis severity is closely associated with lower levels of IL-6 in local joints, suggesting that IL-6 is an important cytokine for maintenance of septic arthritis." (PMID 36262324, 2022). "IL-6 has been known to be involved in acquired immunity and there have been many studies on the pathogenic role of IL-6 in arthritis." (PMID 35566047, 2022). "In humans, severe CHIKV arthritis is associated with elevated serum cytokine/chemokine levels, such as IL-1β, IL-6, TNF-α, CXCL10, etc.." (PMID 36377866, 2022). "IL-6 is a mediator of multiple inflammatory diseases, including arthritis in DNase II–deficient mice." (PMID 34901991, 2022). "In conclusion, we identified a specific increase in NETosis in pGIA joints, and suppression of arthritis by IL-6 blockade associated with decreased neutrophilic infiltration, NETosis in the joints, and plasma citrullinated protein." (PMID 34299252, 2021). "Previous studies have shown that the high concentrations of IL-6 in synovial fluids positively correlate with disease activity and risk of radiographic progression in arthritis." (PMID 35237610, 2021). "Macromolecular HA–EGCG conjugates undergo targeted internalization by CD44-overexpressing fibroblast-like synoviocytes and subsequently cause H2O2-induced cell death and inhibition of IL-6 secretion, thereby suppressing the progression of arthritis." (PMID 35423998, 2021). "Facilitating role of skin inflammation for joint inflammation via crosstalk between keratinocytes and entheseal fibroblasts mediated by IL-6 and IL-23/Th17-associated STAT3 activation." (PMID 34485340, 2021). "Chronic inflammation and arthritis are associated with Prevotella, which induces inflammation by stimulating the production of IL-8, IL-6, and CCL20 through colonic epithelial cells." (PMID 34209270, 2021). "In mice, IL-6 deficiency has been found to lead to a reduction in both the number of arthritic cells in the knee and the collagen-induced arthritis response." (PMID 33036557, 2020). "In contrast, IL-6 knockout mice revealed the progression of more advanced OA than wild-type animals and injection of IL-6 in the joint of IL-6-deficient mice reduced cartilage loss during arthritis." (PMID 32326610, 2020).
Arthritis (continued). "Periodontal alveolar bone loss and IL-6 in gingival tissue were induced by Pg oral infection, as well as severe joint destruction, increased arthritis scores (AS), and both IL-6 and CP productions in serum, joint, and intestinal tissues." (PMID 33076980, 2020). "Reduced production of proinflammatory mediators (e.g., IL-1, IL-6, and different MMPs) along with lessened joint inflammation has been shown in mice with IL17R-deficient streptococcal cell wall-induced arthritis." (PMID 32650733, 2020). "In arthritis, IL-6 causes tiredness, anaemia, and inflammation, as well as damage to bones, cartilage, and tissue; tocilizumab reduces these effects." (PMID 32280950, 2020). "The IL-6 is an inflammatory cytokine that is implicated in the pathogenesis of both, iMCD and RA; however, active arthritis is rare in patients with iMCD." (PMID 31045763, 2019). "Overall, these finding underscore the potential relevance of CTHRC1 as a marker in arthritis pathogenesis and also support our earlier findings showing positive association of CTHRC1 with IL-1β and IL-6 in a mouse model of arthritis." (PMID 31249576, 2019). "In a collagen-induced experimental arthritis model, JQ1 induced attenuation in the arthritis severity score associated to lower serum levels of proinflammatory cytokines, including IL-1β, IL-6, IL-17, and IL-18." (PMID 31780938, 2019). "In the animal model of collagen‐induced arthritis, administration of PGE2 analogue, misoprostol, exacerbated joint inflammation, and this was associated with increased mRNA levels of IL‐23 p19 and other pro‐inflammatory cytokines such as IL‐17, IL‐6 and IL‐1β." (PMID 30381825, 2019). "Myeloid cells of lymphatic vessels and spleen producing IL-6 andIL-1β are responsible for an increase in the amount of Bregs associatedwith arthritis, while CD4+ splenic T cells producing IL-21 activateBregs in experimental arthritis models." (PMID 30397522, 2018). "In IL-6 KO mouse models, mice are protected against arthritis and have decreased osteoclast activity and bone loss." (PMID 30671025, 2018). "When we crossed IL-1 cTg with either IL-6-, IL-17A/F-deficient or Stat3 conditional knockout mice, we observed significant inhibition of arthritis development." (PMID 30361689, 2018). "Overexpression of TNF or enhanced IL-6 signaling due to a gain-of-function mutation of gp130 is sufficient to induce arthritis in mice." (PMID 30466479, 2018). "This increase of IL-6 associated to mBSA/IL-1β-induced arthritis was dose-dependently reduced by the treatment with APC366, or the previous transduction with phSPAG11B/C." (PMID 28587618, 2017). "Arthritis in gp130 F759 mice was considerably inhibited by the deficiency of IL-17 or IL-6, and the combination of IL-17 and IL-6 markedly enhanced the production of IL-6 from FLS." (PMID 28753982, 2017). "Pro-inflammatory cytokines, such as TNF, IL-1, and IL-6, are pathogenic drivers in both RA and in many mouse models of arthritis; however, the impact of each cytokine on the disease progression can differ from patient to patient and from model to model." (PMID 27313578, 2016). "The events that underline the progression of arthritis are mediated by several chemotactic factors such as interleukins (IL-1, IL-6, and IL-10), tumor necrosis factor (TNF-α), interferons (INF-γ) plus leukocytes, and adhesion factors." (PMID 26273477, 2015). "The release of CGRP was also implicated in the generation of pain in arthritis models showing another link between IL-6 and CGRP." (PMID 26590032, 2015). "In an infection model, ISS 4746 and ISS 4749 caused relatively severe arthritis in a higher proportion of mice and induced higher levels of interleukin (IL)-6 and IL-1β in comparison to ISS 3319." (PMID 26452736, 2015). "IL-6 has been associated with pathological conditions such as arthritis, autoimmune and inflammatory responses, and cancer." (PMID 26491692, 2015).
Arthritis (continued). "B6 background IL-38−/− mice developed more severe arthritis than control WT mice, associated with enhanced expression of IL-1β and IL-6 in the ankle joints." (PMID 29124228, 2015). "In the anti-IL-7R treated TSLPR-/- mice, strongly ameliorated clinical arthritis and immunopathology were associated with decreased levels of IL-17-associated cytokines IL-17 and IL-1β locally and IL-6 systemically." (PMID 26110994, 2015). "Mice deficient in IL-6 have reduced arthritis severity coupled with impaired IL-17 production by CD4+ T cells." (PMID 24877127, 2014). "In recent years, many efforts in understanding the pathogenic role of IL-6 in arthritis have been focused on the effect of IL-6 on adaptive immunity." (PMID 25271853, 2014). "In the CIA model, activated T cells produce augmented amounts of both Th1 and Th17 cytokines, while deficiency of IL-6 activity through gene knockout suppresses Th17 cytokine production and clinical symptoms of arthritis." (PMID 24524085, 2014). "Il6 is an important player in the development of chronic joint inflammation and is thought to be involved in osteoarthritis-associated joint inflammation." (PMID 24002865, 2013). "The evidence suggests that, in contrast to IL-6, IL-10 plays an active role in ameliorating arthritis caused by degeneration." (PMID 22550538, 2012). "When paws were matched for maximal clinical disease score (score 3), expression of arthritis-associated genes showed a consistent trend towards reduction in the presence of C17 with a significant reduction observed for IL-6." (PMID 21799806, 2011). "The cytokine interleukin-6 (IL-6) is thought to be a key player in systemic inflammation and arthritis, as shown, for example, by significantly attenuated antigen-induced arthritis in IL-6-deficient mice." (PMID 20626857, 2010). "The inflamed synovial tissue is a major source of IL-6 production, and the blockade of IL-6 or its deficiency reduced the severity of experimental arthritis by impairing the T-cell response." (PMID 19068145, 2008). "The circulating markers of inflammation, CRP and IL6, may also be associated with inflammatory conditions such as arthritis or infections." (PMID 40137085, 2025). "This likely improved his quality of life (relieving arthritis) and helped reduce steroid exposure, but it may have contributed to persistent susceptibility to infections (IL-6 inhibition can also impair host defenses)." (PMID 41181159, 2025). "In the presence of IL-6, nTregs exhibit reduced stability and are prone to differentiate into Th17 cells, which secrete IL-17 a cytokine closely associated with joint inflammation in arthritis." (PMID 39629263, 2024). "In our Risk-RA cohort the finding of increased levels of IL-6 in the Risk-RA phase, something also seen in Pre-RA studies, is a sign of inflammation in individuals progressing to arthritis, although the levels are comparable to the levels in healthy controls (available at Rheumatology online)." (PMID 38457608, 2024). "Similarly, elevated serum IL-6 and IL-17 levels in patients with RA were shown to induce arthritis and cause emotional symptoms, especially depressive symptoms." (PMID 36835939, 2023). "Mice overexpressing IL-6 develop osteopenia as well as severe alterations in trabecular bone microstructure with decreased osteoblasts and increased osteoclast number and activity, whereas IL-6 deficient mice suppress inflammation and bone erosion in an antigen-induced arthritis model." (PMID 35948905, 2022). "Finally, we noted that serum IL‐6 levels were unmodified in Ahr‐ and Il‐22‐deficient mice following arthritis induction." (PMID 33734594, 2021). "While IL-6 serum levels are higher in patients with arthritis, this cytokine has also been associated with severe systemic manifestations such as macrophage activation syndrome, and therapeutic blockade of IL-6 provided excellent clinical responses in SJIA patients with systemic phenotype." (PMID 34203779, 2021).
Arthritis (continued). "Excessive IL6 causes excessive inflammation as seen in arthritis." (PMID 32511341, 2020). "However, the rationale for anti-IL-6 therapy is strong—in arthritis, IL-6 causes tiredness, anaemia, and inflammation and damage to bones, cartilage, and tissue." (PMID 32280950, 2020). "However, although many efforts have focused in understanding the specific pathogenic role of IL6 in adaptive immunity in arthritis, much less is known about the direct effects of IL6 trans-signaling on the synovial inflammatory process." (PMID 33126846, 2020). "The overproduction of IL-6, a proinflammatory cytokine, is associated with a spectrum of age-related conditions, including cardiovascular disease, osteoporosis, arthritis, type two diabetes mellitus, certain cancers, periodontal disease, frailty, and functional decline." (PMID 32244777, 2020). "Indeed, PGE2 secretion was significantly reduced in IL-6-deficient MSCs, which translated into a poor immunosuppressive ability in a collagen-induced experimental arthritis mouse model." (PMID 33318571, 2020). "As the lack of A20 expression in RA BM-MSCs is associated with more IL-6 secretion, and dysregulation of the Th17/Treg balance, this acquired defect of RA BM-MSCs could contribute to arthritis pathogenesis." (PMID 31722720, 2019). "Moreover, P. copri has been associated to enhancing susceptibility to inflammatory disorders like arthritis through intrinsic Th17 promoting capability, driving cytokines IL-6 and IL-23 and has been associated to systemic inflammation status too." (PMID 31379797, 2019). "IL-6 is associated with autoimmune diseases, such as multiple sclerosis, arthritis and enteritis." (PMID 29320456, 2018). "Similarly, a recent study based on collagen-induced arthritis reported a reduction of IL-6 serum levels in mast cell-deficient mice." (PMID 28587618, 2017). "Moreover, IL-6 has been essentially associated with late symptoms such as arthritis and neuroborreliosis, but also with erythema migrans and with late skin symptoms." (PMID 28655322, 2017). "Interestingly, in mice deficient for M3R, abundance of circulating IL-6 was strongly enhanced in mice with low cumulative arthritis score (CAS), while WT mice only showed high plasma IL-6 levels when they reached a high CAS." (PMID 26785775, 2016). "Serum IL-6 levels were shown to be elevated in AS patients, along with factors associated with poor prognosis such as positive HLA-B27, inflammatory lower back pain, and arthritis." (PMID 26339141, 2015). "Thus, IL-6, which is produced by monocytes/macrophages, T cells and synovial fibroblasts, seems to be involved in the systemic events underlying arthritis, especially in the transition phase of its development." (PMID 26658436, 2015). "Furthermore, a number of inflammatory mediators are implicated in the establishment and progression of arthritis, including proinflammatory cytokines such as tumor necrosis factor alpha (TNFα) and interleukin (IL)-6 and IL-17." (PMID 25028072, 2014). "Interestingly, in proteoglycan-induced arthritis, mice deficient in IL-4Rα showed higher IL-1β, IL-6 and MIP1a, whereas levels of IFNγ and autoantibodies were less affected." (PMID 23092393, 2012). "In addition, IL-1β, IL-6, IL-21, and IL-23 support the differentiation of T helper 17 (Th17) cells, suppress the differentiation of regulatory T cells, and cause inflammation of arthritis." (PMID 32958016, 2020). "Moreover, IL-6 which was upregulated in both σB transfected and virus infected cells, seems to be associated with osteoclastogenesis indicating its role towards arthritis stimulation." (PMID 29731966, 2018). "High levels of pro-inflammatory cytokines IL-1, IL-6 and IL-8 were detected in cell supernatants from the patient's lymphocytes and elevated expression of genes encoding a variety of cytokines and chemokines known to be implicated in the pathogenesis of arthritis were also observed." (PMID 20003320, 2009).
Arthritis (continued). "In general, from studies using human patient data and animal models of alphaviral arthritis, acute alphaviral-induced arthritis is hallmarked by increased levels of IFNα/β, IFNγ, TNFα, IL-6, IL-1, IP-10, IL-12, IL-15 and CXCL9MCP-1 (CCL2), and MIF-I." (PMID 41442410, 2026). "Administration of 26 mg/kg of the extract had maximally reduced the symptoms of arthritis, improved protective mediators (IL-4), decreased inflammatory cytokines (IL-1β, IL-6, IL-17, and IFN-γ), and restored joint structure." (PMID 41495193, 2026). "When IL‐6 levels are extremely high in the context of infections (and rarely lupus serositis or arthritis), the buffering capacity is exceeded and the hepatocytes respond by producing CRP." (PMID 41591508, 2026). "IL-6 not only participates in the development of arthritis, autoimmune diseases, and cancer, but also plays a role in tissue repair." (PMID 40809693, 2025). "A total of 6 mg/kg/d for 22 days improved foot-plantar swelling and arthritis scores in RA rats and regulated the balance of pro-inflammatory factors, such as IL-1β, IL-6, and IL-17A, and anti-inflammatory factors, such as IL-4 and IL-10." (PMID 40864815, 2025). "The synergistic interplay of TNF-α, IL-6, and IL-1β establishes a self-amplifying inflammatory loop central to arthritis progression." (PMID 41583484, 2025). "IL-1β, IL-6, IL-8, and TNF-α are small proteins associated with inflammation secondary to arthritis or disk disorders and have an important role in the onset and progression of TMDs." (PMID 40142185, 2025). "Delanzomib decreased the severity of arthritis and reduced the levels of TNFα, IL-6, and CRP in rats with CIA." (PMID 40243560, 2025). "Currently he is managed on combined therapy of ruxolitinib 0.8 mg/kg/day, and the IL-6 inhibitor tocilizumab, that allowed to wean him off steroids and has led to remission of fever, arthritis, kidney disease and stabilization of liver disease." (PMID 41472683, 2025). "Firstly, both conditions involve chronic inflammation, with elevated pro-inflammatory cytokines like IL-6 and TNF-α exacerbating arthritis symptoms and contributing to CVD, a major cause of death in arthritis patients." (PMID 40904459, 2025). "This is demonstrated in murine CIA models, where ICI combinations counteract tumor-induced arthritis suppression by upregulating Ifnar1 and modifying the IL-6/IFN-γ ratio." (PMID 41239350, 2025). "In this model, WT mice exhibited more severe arthritis and greater footpad swelling than IL-6 KO mice, as consistently documented." (PMID 40170729, 2025). "The complete Freund’s adjuvant (CFA)-induced arthritis model is widely used to evaluate the effectiveness of treatments for both acute and chronic inflammation, with IL-6 expression playing a pivotal role in driving the inflammatory process." (PMID 40191469, 2025). "We also determined the concentrations of the cytokines IL-6, IL-10, IFNγ, TNFα, IL-17A, IL-17F, and IL-22 in serum samples of the arthritis patients." (PMID 40806470, 2025). "The anti-TNF/IL-6 bispecific antibody completely inhibits the inflammatory factor CXCL13 in the arthritis model, and its effect is superior to that of the monoclonal antibody combination." (PMID 40932933, 2025). "In a previous study, it was found that the concentration of IL-6 in the joint synovial fluid of various types of arthritis was significantly higher than that in the serum." (PMID 40673198, 2025). "QRHXD and MTX significantly reduced toe swelling and arthritis, decreased inflammatory factors such as IL-1β, IL-6, IL-17, and TNF-α, and increased the anti-inflammatory factor IL-10." (PMID 40124380, 2025). "Arthritis patients with IA and OA were included in the subsequent correlation analysis between IL-6 and DC3 frequencies, to cover a broad range of IL-6 levels." (PMID 40687784, 2025). "Utilizing SF from patients with arthritis, we show that DC3s can develop from DC2s in response to IL-6 and JAK/STAT3 signaling." (PMID 40687784, 2025).